TEK (TEK receptor tyrosine kinase)
Diseases named in the same sentence as TEK in open-access papers (continued):
Sharing a sentence is not in itself a finding about the gene and the disease.
glaucoma (28 papers, 2017 to 2025). Increased pressure in the eyeball due to obstruction of the outflow of aqueous humor. "Insights into TEK’s impact on ocular disease mechanisms may pave the way for innovative diagnostic and therapeutic approaches, offering hope for enhanced care of glaucoma patients." (PMID 38694874, 2024). "Variable disease severity in MYOC mutation carriers has recently been shown to be affected by polygenic effects, and glaucoma variation caused by some TEK mutations may be due to the modifying effects of an SVEP1 variant." (PMID 36453543, 2022). "Second, we performed multi-omics analysis to identify glaucoma-associated genes dysregulated in RCC tissues, with a particular focus on TEK." (PMID 40808675, 2025). "Among the glaucoma-related genes analyzed, TEK has particularly caught our attention due to its downregulated expression and protective role in patient outcomes." (PMID 40808675, 2025). "TEK, a glaucoma-related gene, was downregulated in RCC tissues and correlated with advanced tumor stage and metastasis." (PMID 40808675, 2025). "A Mendelian randomization study suggested a potential association between TEK signaling pathways and elevated intraocular pressure (IOP), a primary risk factor for glaucoma." (PMID 38694874, 2024). "Variants in TEK have been linked to PCG, indicating a substantial genetic basis for this type of glaucoma." (PMID 38694874, 2024). "In summary, understanding TEK’s involvement in glaucoma through genetic, molecular, and functional studies held promise for clinical applications." (PMID 38694874, 2024). "Three hub genes, CD40LG, TEK, and MDK, were validated as potential diagnostic biomarkers for high-risk glaucoma patients, showing increased expression in the NMDA-induced excitotoxicity model." (PMID 38694874, 2024). "In 8 (33%) children with childhood glaucoma one of the following congenital glaucoma associated genes (CYP1B1, FOXC1, LTBP2 and TEK) was confirmed by the genetic examination." (PMID 35144644, 2022). "Heterozygous loss of function variants in TEK or its primary ligand ANGPT1 have been linked to PCG in children, and ANGPT1 and ANGPT2 have been associated with primary open-angle glaucoma (POAG) in adults." (PMID 34663817, 2021). "Additionally, TEK was found to be associated with immune regulation and extracellular matrix (ECM) remodeling—key processes in the progression of both RCC and glaucoma." (PMID 40808675, 2025). "The activation of TEK in Schlemm’s canal region helps ensure proper fluid drainage, thereby contributing to the prevention of increased intraocular pressure, a key factor in glaucoma pathogenesis." (PMID 40808675, 2025). "By utilizing genetic instruments and single-nucleus RNA sequencing data, this study proposed a biological mechanism through which TEK may impact glaucoma pathogenesis." (PMID 38694874, 2024). "While specific studies on glaucoma were not identified, exploring TEK mutations, especially in primary congenital glaucoma (PCG), sheds light on genetic contributions to ocular diseases." (PMID 38694874, 2024). "In 33% of children with glaucoma mutations in the CYP1B1, FOXC1, LTBP2 and TEK genes were found." (PMID 35144644, 2022). "In all eight PCG families, no rare variants except for those observed in TEK were identified in genes previously associated with PCG or later onset forms of glaucoma." (PMID 33027505, 2020). "Furthermore, recent genome-wide association studies have identified risk variants linked to the TEK signaling pathway in adults with elevated IOP and open angle glaucoma, the most common form of glaucoma worldwide." (PMID 31621585, 2019). "Notably, the downregulation of TEK expression also plays a key role in the pathology of glaucoma." (PMID 40808675, 2025).
glaucoma (continued). "Loss of function variants in TEK, or its trabecular meshwork (TM)-expressed ligand ANGPT1 cause primary congenital glaucoma (PCG), a severe form of pediatric glaucoma, in humans and mice and are associated with increased risk of primary open angle glaucoma (POAG) in adults." (PMID 41279337, 2025). "Therefore, shikonin, by upregulating TEK expression, may act on the shared pathological mechanisms of glaucoma and RCC." (PMID 40808675, 2025). "Indeed, a recent study has demonstrated the effectiveness of targeting the Angpt-TEK signaling pathway in a mouse model of glaucoma using an antibody which increases the signaling ability of the context-dependent, weak TEK agonist ANGPT2 by clustering it into higher-order multimers." (PMID 31621585, 2019). "In conclusion, our study provides novel insights into the link between glaucoma and RCC and highlights TEK as a potential therapeutic target." (PMID 40808675, 2025). "Through literature review, several key glaucoma-related genes were identified, including MYOC, TBK1, COL1A1, COL1A2, FOXC1, LRP2, OPTN, and TEK." (PMID 40808675, 2025). "Dysregulation of Angpt-TEK signaling results in hypomorphic or failed SC formation, elevated IOP and glaucoma in mice and humans." (PMID 31621585, 2019). "Interestingly, these glaucoma-related genes like MYOC, TBK1, COL1A1, COL1A2, FOXC1, LRP2, and TEK also showed significant differential expression in RCC tissues." (PMID 40808675, 2025). "Congenital Glaucoma can be caused by the CYP1B1, LTBP2, TEK, and two loci of uncertain function which were not investigated in this research." (PMID 39480826, 2024).
ovarian carcinoma (22 papers, 2009 to 2025). A malignant neoplasm originating from the surface ovarian epithelium. "The topmost comorbidity enriched MOA protein is TEK, angiopoietin-1 receptor; angiopoietins are found to promote ovarian cancer progression." (PMID 36008469, 2022).
vascular malformation (19 papers, 2020 to 2025). A non-neoplastic disorder that is the result of defects of vascular morphogenesis. "Somatic mutations in TIE2/TEK have been implicated in vascular malformations." (PMID 34238334, 2021). "Mutations in PIK3CA, TEK, GNAQ, and GNA11 have been identified in various types of vascular malformations and hemangiomas." (PMID 40428263, 2025). "For this, we isolated and cultured ECs derived from human vascular malformations carrying mutations in PIK3CA and TEK/TIE2, together spanning the genetic causes of more than 80% of low‐flow lesions in patients." (PMID 35695059, 2022). "This selection also contains: i) areas defined as hotspots in cancer but not yet observed in vascular malformations, and ii) hotspot germline variants in RASopathy genes and TEK." (PMID 38778413, 2024). "Most of the frequently found somatic mutations in low-flow vascular malformations occur in genes involved in the mammalian target of rapamycin (mTOR) pathway; for example, PIK3CA and TEK/TIE-2 mutations lead to a gain of function and increased activity of mTOR." (PMID 37153086, 2023). "The identified PIK3CA mutations have been previously reported in other patients with PROS, and the KRAS and TEK mutations in patients with vascular malformation, but the MAP2K3 and TBC1D4 mutations have not been previously reported." (PMID 36175890, 2022). "Namely, TEK rs639225 is a synonymous SNP (sSNP) in exon 13 that may affect splicing regulation by altering the exonic splicing enhancer (ESE) motif and which is associated with vascular malformations." (PMID 32526933, 2020). "In conclusion, we have presented a novel mouse model of vascular malformations and provided encouraging preliminary evidence of alpelisib’s efficacy in patients with either PIK3CA or TEK-related capillary venous malformations." (PMID 38880808, 2024). "Our results might indicate that this therapy is also effective for TEK‐mutant vascular malformations; however, the lack of TEK‐mutant mouse lines precludes the assessment in vivo." (PMID 35695059, 2022).
COVID-19 (18 papers, 2021 to 2025). A disease caused by infection with severe acute respiratory syndrome coronavirus 2. "Among them, Superoxide Dismutase 2 (SOD2, P04179) and TEK Receptor Tyrosine Kinase (TEK, Q02763) have been confirmed as drug targets for COVID-19." (PMID 39192889, 2024). "As we could find a higher expression of TIE2 (TEK) in COVID-19 compared to influenza, non-influenza viral myocarditis, and control samples by nanostring analysis, we performed additional immunohistochemical stains demonstrating TIE2 expression primarily on macrophages." (PMID 36371548, 2023).
ischemia (16 papers, 2009 to 2022). A hypoperfusion of the BLOOD through an organ or tissue caused by a PATHOLOGIC CONSTRICTION or obstruction of its BLOOD VESSELS, or an absence of BLOOD CIRCULATION. "In the kidneys of TEK-CRE PGISfl/fl mice, red blood cells were readily observed in the peritubular capillaries at 24 h after ischemia." (PMID 30413885, 2019).
primary congenital glaucoma (14 papers, 2017 to 2025). "TEK variants with loss‐of‐function are instead associated with primary congenital glaucoma with incomplete penetrance and variable expressivity." (PMID 39498435, 2024). "Rare mutations in the TEK gene that lead to loss of TEK protein function were shown to be present in a subset of families with primary congenital glaucoma (PGC)." (PMID 37996923, 2023). "Even more striking, variants in TEK associated with primary congenital glaucoma were shown to be inherited from an unaffected parent in all families where both parents were tested." (PMID 33973683, 2021). "We previously reported loss of function mutations in the receptor tyrosine kinase TEK or its ligand ANGPT1 cause primary congenital glaucoma in humans and mice due to failure of SC development." (PMID 31621585, 2019). "One of two receptor tyrosine kinases in the angiopoietin/TEK signaling pathway, autosomal dominant mutations in TEK have been identified in patients with primary congenital glaucoma and congenital glaucoma associated with sclerocornea (specific variant not reported)." (PMID 41011222, 2025). "Of the genes known to cause primary congenital glaucoma or anterior segment dysgenesis, LTBP2 and TEK showed marked differentiation from normal control morphology." (PMID 38682030, 2024). "Purposes: Recent studies have suggested that loss-of-function mutations of the tunica intima endothelial receptor tyrosine kinase (TEK) are responsible for approximately 5% of primary congenital glaucoma (PCG) cases in diverse populations." (PMID 34956319, 2021). "However, inactivating TEK variants do not cause a vascular phenotype but can confer an increased risk for primary congenital glaucoma with variable expressivity." (PMID 39498435, 2024).
colorectal cancer (13 papers, 2016 to 2026). A primary or metastatic malignant neoplasm that affects the colon or rectum. "Consistent with this regulatory relationship, a study in colorectal cancer indicated that macrophage-derived SHP-2 can inhibit TEK protein phosphorylation, thereby inactivating the PI3K/AKT/mTOR pathway and suppressing metastasis." (PMID 40808675, 2025).
congenital glaucoma (13 papers, 2017 to 2025). "TEK gene mutations have previously been found in congenital glaucoma families with variable expressivity." (PMID 37386247, 2023). "The intricate genetic landscape of Primary Congenital Glaucoma (PCG) was further complicated by interactions between TEK and CYP1B1 genes, hinting at a digenic mode of inheritance in specific cases." (PMID 38694874, 2024). "We did not identify pathogenic or likely pathogenic variants in other genes known to cause congenital glaucoma, including rare variants (allele frequency <0.001) in ANGPT1, CPAMD8, CYP1B1, MYOC, LTBP2, PITX2, SVEP1, and TEK." (PMID 36453543, 2022). "As THBS1 can contribute to the development of vasculature as well as lymphangiogenesis, we first considered abnormalities in angiogenesis, lymphangiogenesis, or SC development, as has been recently shown for congenital glaucoma causing mutations in ANGPT1 and TEK." (PMID 36453543, 2022). "In the gene knockout groups with genes related to congenital glaucoma, GMDS, FOXC1, LTBP2, TEK, and CYP1B1, no distinct patterns were observed in the transcriptome of these gene knockout groups." (PMID 38272457, 2024).
ischemic stroke (11 papers, 2010 to 2026). A stroke disorder caused by obstruction of blood flow to the brain, due to thrombotic (local blood clot formation) or embolic (due to a blood clot or other material traveling from another site) event. "Because ANGPT2 regulates angiogenesis through TEK and integrin signaling, and promotes neuroprotection in a model of ischemic stroke, the ANGPT2–TEK/ITGA5:ITGB1 signaling axis from EC:Exc3/Exc5 to fibroblasts (EC:Fib) likely represents a resilience-linked angiogenic support mechanism." (PMID 41035073, 2025). "Several variants detected in this study demonstrated suggestive association with outcome (p < 10−5), some of which are within or near genes with experimental evidence of influence on ischemic stroke volume and/or brain recovery (e.g., NTN4, TEK, and PTCH1)." (PMID 30796134, 2019).
diabetic retinopathy (10 papers, 2016 to 2024). "Mutations in the TEK gene are associated with several eye diseases, and Tie2 is a highly investigated target in different conditions such as subretinal and choroidal neovascularization, macular oedema or diabetic retinopathy." (PMID 32180797, 2020).
lung carcinoma (10 papers, 2009 to 2025). "In public microarray datasets, we found that the elevated expression of TEK, which was upregulated in female BE-responsive patients, was associated with increased survival in female lung cancer patients." (PMID 33075110, 2020). "In a study investigating gene expression patterns in non-smoking lung cancer patients, researchers identified ROBO4 and TEK as down-regulated genes compared to healthy individuals, suggesting a potential role for these genes in the development or progression of lung cancer in non-smokers." (PMID 39595659, 2024). "Together our results most clearly highlighted the importance of TEK, LDB2, ATF6 and UBQLN1 in NSCLC patient BE responses, underscoring the value of examining system-level gene interactions in order to better understand the determinants of lung cancer patient therapeutic responsiveness." (PMID 33075110, 2020).
angiosarcoma (9 papers, 2010 to 2024). A malignant tumor arising from the endothelial cells of the blood vessels. "In about 10% of angiosarcomas, mutations in the VEGFR2 or VEGFR3 can be detected, and gene expression profiling shows upregulation of TIE1, VEGFR2, SNRK, TEK (TIE2) and FLT1 (VEGFR1), all playing a role in angiogenesis." (PMID 26474454, 2015). "Strong expression of ANGPT2, TIE1, and TEK mRNAs has been reported in cutaneous angiosarcomas, and Tie2 antagonists inhibit in vitro angiosarcoma cell survival and delay in vivo angiosarcoma tumor growth." (PMID 25374893, 2013). "The top most upregulated genes in angiosarcomas included angiogenic regulators such as TIE1, VEGFR2, SNRK, TEK, and VEGFR1, revealing that aberrant angiogenic signaling is a key feature of this sarcoma." (PMID 25374893, 2013).
pancreatic cancer (9 papers, 2015 to 2025). "Interestingly, myoferlin is also required for angiogenic cascades by maintaining VEGFR2 and TEK expression in endothelial cells, and VEGFA secretion in pancreatic cancer cells." (PMID 35205843, 2022).
bladder cancer (8 papers, 2021 to 2024). "Ablation of METTL3 in bladder cancer stem cells suppresses TEK and VEGFA expression." (PMID 39691597, 2024). "In bladder cancer, METTL3 deletion resulted in reduced m6A abundance in specific regions of tyrosine kinase endothelial (TEK) and VEGF-A mRNA and decreased levels of TEK and VEGF-A mRNA and protein." (PMID 39289775, 2024). "In bladder cancer (BCa), Wang and coworkers found that METTL3 ablation in BCa CSCs suppressed tumor angiogenesis by regulating TEK and VEGFA." (PMID 39691597, 2024). "In contrast, up- or down-regulation of METTL3 in bladder cancer cells can enhance or inhibit the transcriptions and protein expression of TEK and VEGF-A, which are components of the PI3K/AKT pathway respectively, thereby affecting the angiogenesis of bladder cancer via RNA methylation." (PMID 38053093, 2023). "Additionally, METTL3 could promote angiogenesis and metastasis in gastric cancer (GC) and bladder cancer through regulating m6A and mRNA stability of hepatoma-derived growth factor (HDGF), tyrosine kinase endothelial (TEK) and VEGFA, respectively." (PMID 38322265, 2024). "Furthermore, METTL3 could regulate the expression of the TEK and VEGFA genes to promote angiogenesis and exacerbate bladder cancer progression." (PMID 36246403, 2022). "Our findings offer convincing evidence of Mettl3 in epigenetically modifying TEK/PI3K/VEGF cascades involving in angiogenesis, suggesting that therapeutically targeting Mettl3 may provide one of the alternatives for antiangiogenesis therapy in bladder carcinoma." (PMID 33681207, 2021).
blue rubber bleb nevus syndrome (8 papers, 2020 to 2025). "Despite the incomplete understanding of the underlying mechanism of blue rubber bleb nevus syndrome, it is widely accepted that somatic mutations in the TEK gene (TEK receptor tyrosine kinase) play a crucial role in its etiology." (PMID 39867693, 2024). "Somatic mutations in TEK encoding TEK receptor tyrosine kinase are identified in sporadic venous malformation (VM) and blue rubber bleb nevus syndrome (BRBNS)." (PMID 37658401, 2023). "Two patients with blue rubber bleb nevus syndrome carried double somatic TEK mutations, two of which were previously undescribed." (PMID 35740480, 2022). "Blue rubber bleb nevus syndrome is a rare vascular syndrome characterized by the continuous eruption of vascular nodules in the skin, mucous membranes, and solid organs due to somatic activating mutations in the gene coding for the angiopoietin receptor TEK (tunica interna endothelial cell kinase)." (PMID 34449594, 2021). "However, TEK-mediated venous anomalies include a spectrum of phenotypes of varying severity and models of mutation acquisition that are distinctive to sporadic unifocal VM, inherited cutaneo-mucosal VM, sporadic multifocal VM and blue rubber bleb nevus syndrome." (PMID 34698142, 2021). "Blue rubber bleb nevus syndrome (BRBNS) is a rare, often severe disorder known to be caused by TIE2/TEK somatic mutations." (PMID 33194911, 2020).
colon carcinoma (8 papers, 2014 to 2025). "(i) In total, 105 plants (33 edible) were found to interact with 4 target proteins (TEK, KDR, FGR1 and TOP1) of the FDA approved colon cancer drugs and 43 of their first-degree neighbors." (PMID 24886433, 2014).
pulmonary hypertension (8 papers, 2012 to 2024). Increased pressure within the pulmonary circulation due to lung or heart disorder. "TEK (angiopoietin-1 receptor) regulates angiogenesis and endothelial cell survival, and is associated with pulmonary hypertension and cutanomucosal venous malformation in humans." (PMID 31683933, 2019).
brain tumors (7 papers, 2008 to 2026). "TEK was also shown to be a key molecular regulator of pathological vascularization in a number of preclinical brain tumor models." (PMID 26083629, 2015).
hemangioma (7 papers, 2009 to 2025). A benign vascular lesion characterized by the formation of capillary-sized or cavernous vascular channels. "Targeted deletion of TEK contributed to postnatal degeneration of newly formed veins and development of hemangioma-like vascular tufts in mouse retina." (PMID 32612536, 2020).
leukemia (7 papers, 2014 to 2025). A malignant (clonal) hematologic disorder, involving hematopoietic stem cells and characterized by the presence of primitive or atypical myeloid or lymphoid cells in the bone marrow and the blood. "Alterations in TEK expression have been observed in many cancers, such as oral squamous cell carcinoma; leukemia; and breast, gastric, and thyroid cancers." (PMID 35222525, 2022).